CDK5 (cyclin dependent kinase 5)
Diseases named in the same sentence as CDK5 in open-access papers (continued):
Sharing a sentence is not in itself a finding about the gene and the disease.
Alzheimer disease (continued). "CRMP2 serves as a physiological target for the kinases glycogen synthase kinase-3β (GSK-3β) and cyclin-dependent kinase 5 (Cdk5), both of which show heightened activity in Alzheimer’s disease." (PMID 40358171, 2025). "The conversion of p35 to p25, triggered by neurotoxic insults such as amyloid-β, leads to prolonged and aberrant Cdk5 hyperactivation, a key pathological driver in Alzheimer’s disease." (PMID 41369365, 2025). "Investigation of Alzheimer’s disease unveiled also a new interaction between CDK5 and the p38 pathway." (PMID 39800748, 2025). "Beyond synaptic dysfunction, the sustained presence of SASP mediators promotes τ hyperphosphorylation, a hallmark of Alzheimer’s disease, through the dysregulation of kinases such as glycogen synthase kinase 3β (GSK-3β) and cyclin-dependent kinase 5 (CDK5)." (PMID 40149940, 2025). "In the Deregulated CDK5 Triggers Multiple Neurodegenerative Pathways in Alzheimer’s Disease (R-HSA-8862803.4) pathway, it interacts with YWHAE (14–3-3ε), stabilizing the cytoskeleton and modulating stress responses." (PMID 40018519, 2025). "In Alzheimer’s disease (AD), Cdk5-induced GA fragmentation mediated by GRASP65 protein promotes amyloid precursor protein trafficking." (PMID 38349608, 2024). "Our results provide a structural basis for the development of novel drugs targeting the 5-HT7R/CDK5 interaction interface for the selective treatment of Tau-related disorders, including frontotemporal dementia and Alzheimer’s disease." (PMID 38641599, 2024). "The second most significant association was observed for EWR_Total with the ‘Deregulation of CDK5 in Alzheimers Disease’ pathway (BioCarta) (FDR corrected p = 1.62E-03)." (PMID 38538593, 2024). "The qRT-PCR analyses also showed the upregulation of Cdk5 and Prkca, which are involved in the pathogenesis of Alzheimer’s disease via tau phosphorylation in several sites." (PMID 38473758, 2024). "GSK3β and cdk5 are two major tau kinases whose activity is increased and prolonged in Alzheimer’s disease, however, it is also known that cdk5 is a negative regulator of GSK3β and inhibits its activity by increasing its phosphorylation on serine-9." (PMID 39520508, 2024). "One study demonstrated that quercetin-nanoparticle-loaded exosomes showed enhanced bioavailability with a therapeutic effect in Alzheimer’s disease by inhibiting cyclin-dependent kinase 5 (CDK5), facilitating tau protein phosphorylation." (PMID 38474512, 2024). "For example, honokiol has been shown to suppress the CDK5-involved signaling pathway to ameliorate cognitive deficits in the Alzheimer’s disease mouse model (TgCRND8 mouse) via the modulation of the gut microbiota." (PMID 39519833, 2024). "Cdk5 was concurrently identified as tau protein kinase II, linking Cdk5 to the paired helical filaments that accumulated in the brains of Alzheimer’s disease (AD)." (PMID 39235580, 2024). "Abnormal CDK5 function is involved in the pathological process of many neurodegenerative diseases, including Alzheimer's disease, Parkinson's disease, and stroke." (PMID 36964998, 2023). "Cdk5 is dysregulated in various neurological disorders, including Alzheimer’s disease, Parkinson’s disease, and amyotrophic lateral sclerosis (ALS)." (PMID 36899941, 2023). "A study showed plasma-derived exosome-loaded QCT nanoparticles showed improved bioavailability with therapeutic effect in Alzheimer’s disease by inhibiting cyclin-dependent kinase 5 (CDK5) facilitated phosphorylation of protein Tau." (PMID 36569877, 2022). "In the male SNO protein dataset, proteins were found to be involved in networks designated as “FCERI-mediated NF-κB activation network,” “Deregulated CDK5 triggers multiple neurodegenerative pathways in Alzheimer’s disease models,” and “WNT signaling”." (PMID 36516243, 2022).
Alzheimer disease (continued). "Initial enthusiasm for anti-Cdk5 treatment for neurodegenerative diseases such as Alzheimer’s disease (AD) led to the generation of a number of lead compounds which showed reasonable potency in vitro." (PMID 35645825, 2022). "Cdk5 hyperactivation contributes to several neurodegenerative diseases, including Alzheimer’s disease (AD), Parkinson’s disease (PD), and Huntington’s disease (HD; Cheung and Ip, 2012)." (PMID 35966199, 2022). "In the pathway analysis of KANPHOS, a search for Alzheimer’s disease pathways reveals that CDK5 and GSK3β are important kinases involved in the pathogenesis of Alzheimer’s disease." (PMID 35011609, 2021). "CDK5, a cyclic-dependent protein kinase, has been found to be closely related to the occurrence of Alzheimer's disease." (PMID 34987593, 2021). "In view of the role of CDK5 in the pathogenesis of Alzheimer's disease, it is possible to treat Alzheimer's disease by interfering with the high activity of CDK5." (PMID 34987593, 2021). "Defective cdk5/p35 activity and damage to axonal transport are both features of Alzheimer’s disease." (PMID 31068217, 2019). "It is reported that CDK5 phosphorylates tau at the hyperphosphorylated sites in Alzheimer’s disease (AD) brains." (PMID 31698798, 2019). "Understanding these mechanisms is essential for properly comprehending p35 and cdk5 function in neurons and also its dysfunction in Alzheimer’s disease." (PMID 31068217, 2019). "Deregulation of Cdk5 is reported to be involved in many neurodegenerative diseases, such as Alzheimer’s disease (AD) and PD." (PMID 29910724, 2018). "The deregulation of Cdk5 activity was observed in post mortem analysis of brain tissue of Alzheimer’s disease (AD) patients, suggesting the involvement of Cdk5 in the pathomechanism of this neurodegenerative disease." (PMID 29301548, 2018). "Previously, we have demonstrated that adeno-associated virus serotype-9 (AAV9) mediated Cdk5 inhibitory peptide (CIP) inhibits the activity of Cdk5/p25 complex and alleviates pathologic and behavioral changes in Alzheimer’s disease mouse model." (PMID 29910724, 2018). "Involved in the pathology of Alzheimer’s disease through the deregulated activity of cyclin-dependent kinase 5 (Cdk5), and also involved in synaptic plasticity, and learning and memory." (PMID 29066959, 2017). "In this study, using a molecular docking method to screen a virtual library, we discovered molecules that can simultaneously inhibit Glycogen synthase kinase-3 beta and cyclin-dependent kinase 5 as lead compounds for the treatment of Alzheimer's disease." (PMID 28179579, 2017). "TFP5, a modified 24-aa peptide (Lys254-Ala277) derived from p35, was found to effectively inhibit CDK5 hyperactivity and improve the outcomes of Alzheimer’s disease and Parkinson’s disease in vivo." (PMID 28045138, 2017). "7-bromoindirubin-3-oxime (7Bio), an indirubin derivative derived from indirubin-3-oxime, possesses inhibitory effects against cyclin-dependent kinase-5 (CDK5) and glycogen synthase kinase-3β (GSK3β), two pharmacological targets of Alzheimer's disease (AD)." (PMID 29234273, 2017). "Our previous work showed that in the early stages of Alzheimer’s disease expression of cyclin-dependent kinase 5 (Cdk5) activator p25 is reduced (Engmannet al., 2011)." (PMID 27524794, 2016). "The initiation of Golgi complex fragmentation in Alzheimer’s disease has been reported to involve Cdk5 phosphorylating the pH-sensitive cis-Golgi protein GM130, and subsequently, GM130 is digested in lysosome." (PMID 25790952, 2016). "We found that the truncated cyclin-dependent kinase 5 activator p25 is reduced in Alzheimer’s disease." (PMID 25631211, 2015). "Hyperactivity of Cdk5 has been reported in neurodegenerative disorders including Alzheimer’s disease, Parkinson’s disease and amyotrophic lateral sclerosis." (PMID 23688022, 2013).
Alzheimer disease (continued). "Because of the similarities between neurons and pancreatic β cells and between the neural degeneration of Alzheimer's disease and the deterioration of pancreatic β-cell functioning, CDK5 plays an important role in the pathogenesis of diabetes mellitus." (PMID 22028710, 2011). "CDK5 is a serine/threonine kinase ubiquitously expressed in the mammalian tissues, with best characterized functional role in the Alzheimer's disease." (PMID 22028710, 2011). "Over-activity of the p35/Cdk5 complex has also been associated with hyperglycemia and has been implicated in the hyperphosphorylation of MAP and tau in Alzheimer's disease." (PMID 19834568, 2009). "CDK5 and especially its partner p25 play a role in the pathogenesis of Alzheimer’s disease." (PMID 39800748, 2025). "This study focused on the abnormal phosphorylation of tau and its aggregation process, characteristic of Alzheimer’s disease, and aimed to compare the morphology and formation process of phosphorylated tau aggregates produced by four kinases: Cdk5/p25, GSK3β, MARK4, and p38α." (PMID 41155414, 2025). "Based on pathological examinations of the brain in Alzheimer’s disease, two proteins, cyclin-dependent kinase 5 (Cdk5) and glycogen synthase kinase 3β (GSK3β), may be involved in the abnormal phosphorylation of tau." (PMID 37754222, 2023). "This suggests that CDK5 inhibitors could be a promising approach in the treatment of neurodegenerative disorders such as Alzheimer's disease, where tau phosphorylation and neuroinflammation play critical roles in the pathology." (PMID 37638222, 2023). "The most notable pathophysiological role of CDK5 was shown in Alzheimer’s disease." (PMID 37760412, 2023). "The results of pathological examination of the brain in Alzheimer’s disease suggest that two proteins, cyclin-dependent kinase 5 (Cdk5) and GSK3β, may be involved in the hyper-phosphorylation of tau." (PMID 37754222, 2023). "However, in addition to these physiological roles, CDK5 is also suggested to be involved in the pathogenesis of many neurodegenerative diseases including Alzheimer's disease (AD), as it is a major tau protein kinase." (PMID 37638222, 2023). "Cdk5 is intimately related to the pathological mechanism of a variety of neurological disorders, such as A-β protein formation in Alzheimer’s disease, mitochondrial fragmentation in cerebral ischemia, and apoptosis of dopaminergic neurons in Parkinson’s disease." (PMID 35966199, 2022). "However, abnormal activation of CDK5 can lead to synaptic inhibition, resulting in the early pathological changes of Alzheimer’s disease (AD)." (PMID 35557834, 2022). "Rs13301996 is intronic to CDK5RAP2, which encodes a regulator of CDK5 activity, interacts with CDK5R1 and pericentrin (PCNT), plays a role in centriole engagement and microtubule nucleation and has been linked to primary microcephaly and Alzheimer’s disease." (PMID 34165540, 2021). "Cdk5 plays a crucial role in regulating the cytoarchitecture of the central nervous system; however, it is clear that Cdk5 can play a role in cell types other than neurons and in the pathogenesis of certain diseases, such as cancer and Alzheimer's disease." (PMID 32352232, 2020). "However, the proteolytic cleavage of p35 to p25 leads to prolonged and aberrant Cdk5 activation and results in synaptic depression, highly mimicking the early pathology of Alzheimer’s disease (AD)." (PMID 32670025, 2020). "In addition, damage to p35 leading to altered cdk5/p35 activity is believed to contribute to the pathogenesis of Alzheimer’s disease." (PMID 31068217, 2019).
Alzheimer disease (continued). "Therefore, RNA interference (RNAi) targeting of Cdk5 reduces tau phosphorylation and decreases the number of neurofibrillary tangles in the hippocampus of triple-transgenic Alzheimer’s disease (AD) mice." (PMID 31371703, 2019). "Moreover, like cdk5/p35, both PP1 and GSK-3β are strongly linked to the pathogenesis of Alzheimer’s disease." (PMID 31068217, 2019). "Since we show that LMTK2 mediates axonal transport of p35 and cdk5, this loss of LMTK2 may contribute to the cell body cdk5/p35 accumulation that has been described in Alzheimer’s disease." (PMID 31068217, 2019). "Moreover, abnormal cell body accumulation of cdk5/p35 is observed in affected regions in post-mortem Alzheimer’s disease brains." (PMID 31068217, 2019). "Since siRNA loss of LMTK2 perturbed axonal transport of both p35 and cdk5, we enquired whether LMTK2 levels might be altered in Alzheimer’s disease." (PMID 31068217, 2019). "Considering that the specific functions of CDK5 in the nervous system and in Alzheimer’s disease by tau phosphorylation, CDK5-dependent VPS34 phosphorylation and the following inhibition of the complex may underlie the molecular basis of neurodegeneration." (PMID 30572663, 2018). "CDK5 and p35/p25 may play a role in the pathogenesis of Alzheimer’s disease(AD) leading to abnormal phosphorylation of substrates such as tau15." (PMID 29651006, 2018). "Accordingly, dysregulation of Cdk5 has been observed in numerous brain diseases, including schizophrenia and epilepsy and neurodegenerative disorders, including Huntington’s disease, Alzheimer’s disease and Amyotrophic Lateral Sclerosis (ALS)." (PMID 29227247, 2017). "This is consistent with increased Cdk5 activity reported for multiple Alzheimer’s disease models which in turn may contribute to the Cdk5-dependent phosphorylation of Tau as a possible contribution to the progression of Alzheimer’s disease." (PMID 29227247, 2017). "Previous studies of CDK5 mainly focused on the neurological disorders, such as Alzheimer’s disease." (PMID 27406233, 2016). "This inappropriate activation of CDK5 has been reported in neuronal death involved in the pathophysiology of several neurodegenerative diseases, including Alzheimer's disease, amyotrophic lateral sclerosis, Parkinson's disease, and prion-related encephalopathies." (PMID 27651795, 2016). "This suggests that Cdk5-mediated phosphorylation of tau may be decreased in Alzheimer’s disease, whereas due to decreased inhibition by Cdk5 glycogen synthase kinase 3β-mediated tau phosphorylation may be increased." (PMID 27524794, 2016). "Our recent work on the cyclin-dependent kinase 5 activator p25 suggested that expression of the multifunctional presynaptic molecule cysteine string protein alpha (CSPalpha) may be affected in Alzheimer’s disease." (PMID 25631211, 2015). "However, deregulation, in particular, hyper-activation of Cdk5 is one key contributor to the pathogenesis of some neurodegenerative diseases including Alzheimer’s disease (AD) and Parkinson’s disease (PD)." (PMID 25875370, 2015). "MiR-103a-3p and miR-107 have been recently shown to target human CDK5R1, coding for the regulatory subunit 1 of cyclin-dependent kinase 5, a protein found to be hyperactivated in different neurodegenerative diseases, including Parkinson’s and Alzheimer's diseases." (PMID 25304816, 2014). "Cdk5, a proline-directed serine/threonine kinase, plays an important role in the physiological functions such as synaptic plasticity, memory formation, and some diseases including Alzheimer’s disease, Parkinson’s disease, and hippocampal sclerosis." (PMID 23688022, 2013). "Accordingly, an increased level of p35 might be caused by an increase of protein stabilization by BDNF and/or by an up-regulation following a down-regulation of miR-107, leading to hyperactivation of CDK5 in Alzheimer's disease." (PMID 21625387, 2011).
Alzheimer disease (continued). "CDK5 is predominantly expressed in post-mitotic neurons and plays an important role in the pathological process of neurological diseases, including Alzheimer’s disease (AD), Parkinson’s disease (PD), cerebral ischemic injury, amyotrophic lateral sclerosis, and Huntington’s disease." (PMID 39390372, 2024). "Furthermore, the review points out that COX-2 enzymes have a relationship with kinase enzymes, including Cyclin Dependent Kinase 5 (CDK5) and Glycogen Synthase Kinase 3β (GSK3β), which are known to play a role in tau phosphorylation and are strongly associated with Alzheimer's disease." (PMID 37638222, 2023). "In addition, the imbalance of CDK5 activity may play a role not only in AD (Alzheimer’s disease), but also in several neurodegenerative diseases." (PMID 35006426, 2021). "Additionally, CDK5 contributes to neurodegenerative diseases such as Alzheimer’s disease (AD)." (PMID 31395805, 2019). "Besides ALS and Alzheimer’s disease, CDK5 might be involved also in the pathogenesis of Parkinson." (PMID 39800748, 2025). "FOXQ1 also reportedly binds directly to inhibit prostaglandin-endoperoxide synthase 2 (PTGS2), and cyclin-dependent kinase 5 (CDK5) to promote apoptosis and inflammation while inhibiting neurite outgrowth in Alzheimer Disease." (PMID 41347087, 2025). "Cyclin-dependent kinase 5 (CDK5) affects neuronal apoptosis and plays a role in the development of Alzheimer’s disease, amyotrophic lateral sclerosis, and ischemic stroke." (PMID 40650017, 2025). "Alzheimer’s disease and nuclear-relevant phosphorylated forms of tau can be produced by incubation with tau’s kinases, including MAPK, cdk5, CAMKII, GSK-3β, and PKA75." (PMID 38429335, 2024). "Similarly, hyper-phosphorylation of tau protein by kinases such as cyclin-dependent kinase 5 (CDK5) and glycogen synthase kinase 3β (GSK3β) has been implicated in the formation of neurofibrillary tangles that have been associated with development of Alzheimer’s disease." (PMID 38450154, 2024). "In addition, according to existing research evidence, CDK5 induces the release of heat shock protein 70 (HSP70) by mediating the degradation of Bcl‐2‐associated athanogene 3 (BAG3) protein, leading to synaptic dysfunction in the pathogenesis of Alzheimer's disease." (PMID 36964998, 2023). "Both Cdk5 and RPM-1 are involved in axon degeneration, and genetically interact with players involved in Alzheimer’s disease, such as Tau and tubulin acetyltransferase." (PMID 35421092, 2022). "According to the Alzheimer’s disease pathway (hsa05010), we listed the main AO targets that regulate tau phosphorylation, such as MAPT, GSK3B, CDK5, CDK5R1, and CAPN1." (PMID 36533181, 2022). "ADAM17, BACE1, CAPN1, CDK5, EIF2AK3, GRIN2B, and GSK3B were enriched in the Alzheimer disease pathway (hsa05010)." (PMID 33807157, 2021). "Cyclin-dependent kinase-5 (Cdk5) increases amyloid beta levels through FOXO3 activity and induces the pathogenesis of Alzheimer’s disease." (PMID 31323047, 2019). "Kinase inhibition of the final compounds was evaluated on a panel of four Ser/Thr kinases (DYRK1A, CDK5, CK1 and GSK3) chosen for their strong implications in various regulation processes, especially Alzheimer’s disease (AD)." (PMID 25268714, 2014). "Together, they mitigate CDK5-induced neurodegeneration by regulating Tau hyperphosphorylation, oxidative stress, and neuronal apoptosis, making FAM110B and YWHAE potential therapeutic targets in Alzheimer’s disease." (PMID 40018519, 2025). "Our data provide evidence that endothelial VEGF-A/Cdk5 signaling mediates neutrophil-trafficking molecules, highlighting that brain endothelial VEGF-A/Cdk5 may serve as a potential therapeutic target for Alzheimer’s disease." (PMID 37280283, 2023). "Another study on Alzheimer’s disease (AD) revealed that the S-nitrosylation transfer reaction mediated by UCH-L1, Cdk5, and Drp1 may play an important role in the occurrence and development of AD." (PMID 34440645, 2021).